AQP3 (aquaporin 3 (Gill blood group))
Diseases named in the same sentence as AQP3 in open-access papers (continued):
Sharing a sentence is not in itself a finding about the gene and the disease.
Crohn disease (3 papers, 2016 to 2023). A gastrointestinal disorder characterized by chronic inflammation involving all layers of the intestinal wall, noncaseating granulomas affecting the intestinal wall and regional lymph nodes, and transmural fibrosis. "Thus, AQP3 modulation was suggested with great potential for disorders associated with abnormal enterocyte proliferation, such as Crohn’s disease." (PMID 35187089, 2022). "Furthermore, the expression of AQP3 was significantly reduced in the ileal mucosa of patients with Crohn’s disease at early stage (Ricanek al., 2015)." (PMID 38089478, 2023). "Apart from the changes of AQP3 expression, previous study showed that AQP3 has one N-glycosylation site, and the misrouting of AQP3 structure may result in fluid imbalance, thus impacting Crohn’s disease and ulcerative colitis." (PMID 38089478, 2023). "Moreover, it has been indicated that the structural changes of AQP3 and AQP10 in human intestine may lead to fluid imbalance, thus facilitating the development of Crohn’s disease and ulcerative colitis." (PMID 27589719, 2016).
gastric tumor (3 papers, 2012 to 2024). "This approach should encompass extensive in vitro and in vivo studies using various GC cell lines and animal models, such as mice with xenografted gastric tumors, so as to validate the role of AQP3 and RGP-induced ferroptosis within a complex biological context." (PMID 38051132, 2024). "AQP3 protein expression was evaluated by IHC and H. pylori infection by modified Giemsa staining in 89 human gastric tumor tissue specimens and corresponding non-cancerous mucosa in the antrum." (PMID 23152856, 2012).
nephrotic syndrome (3 papers, 2008 to 2025). A collection of symptoms that include severe edema, proteinuria, and hypoalbuminemia; it is indicative of renal dysfunction. "There is a marked downregulation of both AQP2 and AQP3 expression, which could be a physiologic response to extracellular water reabsorption in patients with nephrotic syndrome." (PMID 20142913, 2008). "In addition, a 70% decrease in AQP3 expression has been reported in the inner medulla, during induced nephrotic syndrome, which could be a physiological response to extracellular water reabsorption." (PMID 36038817, 2022).
oligohydramnios (3 papers, 2016 to 2023). A lower than normal quantity of amniotic fluid in the amniotic sac as compared to normal values. "Therefore, this study first identified the differences in AQP1 and AQP3 protein expression between the women with normal pregnancy and those with isolated oligohydramnios." (PMID 37386378, 2023). "Also, salvia miltiorrhiza extract is effective in treating oligohydramnios clinically, and it was able to increase AQP3 expression in amniotic epithelial cells." (PMID 37386378, 2023). "Additionally, the expression of AQP3 in placental trophoblasts from patients with oligohydramnios was dramatically decreased (P < 0.05)." (PMID 32542408, 2020). "Compared with normal AFV group, AQP1 protein expression in hAECs was significantly increased in the isolated oligohydramnios group, while AQP3 protein expression was not significantly different." (PMID 37386378, 2023). "Interestingly, in hAECs from pregnant women with isolated oligohydramnios, Tanshinone IIA decreased AQP1 protein expression and increased expression of AQP3." (PMID 37386378, 2023). "Therefore, Tanshinone IIA decreased the expression of AQP1 and AQP3 in hAECs from pregnant women with normal AFV, and Tanshinone IIA decreased AQP1 protein expression and increased the AQP3 expression in hAECs from pregnant women with isolated oligohydramnios." (PMID 37386378, 2023).
skin aging (3 papers, 2022 to 2024). The gradual irreversible changes in structure of skin that occur as a result of the passage of time.. "The expressions of matrix metalloproteinase (MMP)-1, MMP-2, and MMP-9 that represent skin aging were also decreased, whereas moisturizing protein aquaporin-3 (AQP-3) was increased in HaCaT cells and CCD-966SK dermal fibroblasts." (PMID 36983027, 2023). "In order to develop effective natural materials that can prevent skin aging, new materials were sought through in vitro evaluation focusing on AQP3, HAS3, and MMP-1 mechanisms." (PMID 36250021, 2022).
skin squamous cell carcinoma (3 papers, 2014 to 2020). A carcinoma arising from the squamous cells of the epidermis. "Studies have reported that human skin squamous cell carcinoma overexpresses AQP3 and inhibition of its function may alleviate skin tumorigenesis." (PMID 32351935, 2020).
type 2 diabetes (3 papers, 2019 to 2025). "AQP3 levels in the skin were decreased in type 2 diabetes, and this decrease in AQP3 may be one of the causes of xeroderma." (PMID 33494453, 2021). "We aimed to clarify the roles of cutaneous water channel aquaporin-3 (AQP3) in diabetic xeroderma using type 2 diabetes model db/db mice." (PMID 33494453, 2021). "Therefore, in this study, we clarified the overall role of cutaneous AQP3 in the development of diabetic xerosis using type 2 diabetic model mice to investigate new preventive and therapeutic methods targeting AQP3." (PMID 33494453, 2021). "Therefore, we focused on inflammation as the mechanism of the decrease in AQP3 in type 2 diabetes and performed an analysis." (PMID 33494453, 2021). "In summary, xeroderma during type 2 diabetes may occur as a result of a decrease in cutaneous AQP3 as observed in type 1 diabetes." (PMID 33494453, 2021). "Why did the expression level of cutaneous AQP3 decrease during type 2 diabetes?" (PMID 33494453, 2021). "Furthermore, the expression level of AQP3 in the skin was revealed to be decreased at both the mRNA and protein levels with the progression of type 2 diabetes." (PMID 33494453, 2021). "We investigated whether dryness of the skin during type 2 diabetes is related to the altered expression of AQP3, which plays an important role in maintaining the dermal water content." (PMID 33494453, 2021). "Therefore, systemic and local inflammation in the skin may occur during type 2 diabetes, which may decrease AQP3." (PMID 33494453, 2021). "Therefore, xeroderma during type 2 diabetes may occur as a result of a decrease in cutaneous AQP3, which limits the movement of water from the vascular side of the skin to the stratum corneum, as observed in type 1 diabetes." (PMID 33494453, 2021). "In the mechanism analysis, we focused on inflammation, especially tumor necrosis factor-α (TNF-α), based on the report that inflammation is induced in type 2 diabetes patients and that TNF-α regulates the expression of skin AQP3." (PMID 33494453, 2021).
ulcerative colitis (3 papers, 2016 to 2023). An inflammatory bowel disease involving the mucosal surface of the large intestine and rectum. "In diarrhea-type ulcerative colitis patient, AQP3 level in colon was significantly reduced compared with healthy volunteers, while it was increased in morphine-treated constipated animals." (PMID 31877639, 2019).
acute respiratory failure (2 papers, 2016 to 2022). Life-threatening respiratory failure that develops rapidly. "In conclusion, we showed that water and ion channels are altered in patients with acute respiratory failure due to DAD, with an increase in AQP3, AQP5 and Na-K-ATPase expression and a decrease in ENaC expression." (PMID 27835672, 2016). "In the present study, we found that the expression of water and ion channel proteins in the alveolar septum are altered in patients with acute respiratory failure due to DAD, with an increase in AQP3, AQP5 and Na-K-ATPase and a decrease in ENaC compared to control subjects." (PMID 27835672, 2016).
allergic asthma (2 papers, 2016 to 2022). A asthma with a basis in a pathological type I hypersensitivity reaction. "Furthermore, Aqp3–/– and Duox1–/– mice had decreased leukocyte recruitment in models of allergic asthma, and Duox1–/– mice have increased susceptibility to influenza." (PMID 36166305, 2022). "In conclusion, our current findings provide evidence that AQP3 mediates not only T cell trafficking but chemokine production of M2 polarized AMs partly through regulating the amount of cellular H2O2, in the OVA-induced allergic asthma model." (PMID 27165276, 2016).
Ascites (2 papers, 2021 to 2025). Accumulation of fluid in the peritoneal cavity (between the layers of the peritoneum that lines the abdomen). "Besides, AQP3 is primarily expressed in colon, where it plays crucial role in regulating water absorption from the luminal side to the vascular side of the colon, and thereby modulates fluid metabolism during the development of ascites." (PMID 41044610, 2025). "TDEE and its diterpenoids can inhibit the reabsorption and concentration of water in the kidneys by reducing the expression levels of AQP1, AQP2, AQP3 and AQP4, thereby resolving ascites." (PMID 33578967, 2021).
atrophic gastritis (2 papers, 2016 to 2023). "Besides, AQP3 and other AQPs (AQP5, AQP7 and AQP11) were also upregulated at the mRNA level in atrophic gastritis." (PMID 27589719, 2016).
autoimmune disease (2 papers, 2022 to 2024). A disorder resulting from loss of function or tissue destruction of an organ or multiple organs, arising from humoral or cellular immune responses of the individual to their own tissue constituents. "Although little is known about the role of AQP3 as an allergen or autoantigen, other aquaporins have been studied for their relevance as antigens in autoimmune diseases." (PMID 39310813, 2024).
breast invasive ductal carcinoma (2 papers, 2015 to 2017). "Increased AQP3 expression correlated with higher histopathological grade and increased spreading to lymph nodes in patients with invasive breast ductal carcinoma." (PMID 28991174, 2017). "Using immunohistochemistry (IHC) and immunoreactivity scoring system (IRS), we examined the expression level of AQP3 protein in breast invasive ductal carcinoma samples obtained from 56 patients." (PMID 26219409, 2015). "In this study, we explored the relationship between AQP3 expression level in ER-positive breast cancer and the clinical characteristics of patients with breast invasive ductal carcinoma, by immunohistochemistry." (PMID 26219409, 2015). "Similarly, in a study of patients with breast invasive ductal carcinoma, increased expression of AQP3 was observed." (PMID 28991174, 2017).
colon diseases (2 papers, 2022 to 2024). "Together, these findings propose MOMAST® as a potential adjuvant in colon diseases associated with abnormal cell growth by targeting AQP3." (PMID 39857360, 2024). "The obtained results suggest that the AVP-dependent AQP3 pathway might represent a possible target in colon diseases associated with abnormal cell growth." (PMID 35874817, 2022). "Nevertheless, the obtained data suggest that the AVP-dependent AQP3 pathway might represent a novel target in colon diseases associated with abnormal cell growth." (PMID 35874817, 2022). "Overall, data suggest that dDAVP, through the V1aR dependent pathway, reduces AQP3 mediated glycerol uptake, a process that is reversed in adenocarcinoma, suggesting that the AVP-dependent AQP3 pathway may represent a novel target in colon diseases associated with abnormal cell growth." (PMID 35874817, 2022).
COVID-19 (2 papers, 2022 to 2024). A disease caused by infection with severe acute respiratory syndrome coronavirus 2. "Recently, in a GWAS study, 49 variants were associated with the most severe forms of COVID-19, showing that the AQP3 gene had an intense relationship with the most critical picture of infection, a fact that corroborates other studies." (PMID 38543725, 2024). "Another study developed in 34 Spanish hospitals with 11,939 positive cases of COVID-19 identified the relationship of the AQP3, ARHGAP27, ELF5, IFNAR2, LIMD1, OAS1 and UPK1A genes with the severity of the disease." (PMID 38543725, 2024). "Therefore, the objective of our study is to investigate genetic variants in the genes AQP3, ARHGAP27, ELF5, IFNAR2, LIMD1, OAS1 and UPK1A, which were selected due to the association of these genes with the severity of COVID-19, in a sample of Amazonian indigenous peoples." (PMID 38543725, 2024). "Seven new genes (AQP3, ARHGAP27, ELF5, IFNAR2, LIMD1, OAS1 and UPK1A) were related to the severity of COVID-19 in populations of European origin." (PMID 38543725, 2024).
Diarrhea (2 papers, 2020 to 2023). Abnormally increased frequency (usually defined as three or more) loose or watery bowel movements a day. "Diarrhea is commonly associated with abnormal water metabolism in the intestine, which is regulated by AQP3, AQP4, and AQP8 proteins." (PMID 37237988, 2023).
disc degeneration (2 papers, 2022 to 2025). "While AQP3 downregulation is associated with disc degeneration, its function in apoptosis under hyperosmotic conditions remains unclear." (PMID 41262548, 2025). "Our findings indicate that AQP3 deficiency under hyperosmotic conditions contributes to NPC apoptosis by suppressing the PI3K/AKT/mTOR signaling pathway, potentially establishing a pathological cycle of disc degeneration." (PMID 41262548, 2025).
dry mouth (2 papers, 2023 to 2025). "Compared to healthy controls, patients with Sjögren’s syndrome and dry mouth had lower mRNA expression but higher immunoreactive intensities of AQP3 in their salivary glands." (PMID 40725460, 2025). "It is interesting to note that for every one-unit increase in salivary concentration of AQP-3, the odds of being xerostomic increased 42.93 times and for every one-unit decrease in BMI, the odds of having xerostomia increased 0.85 time." (PMID 37027451, 2023). "Binary logistic regression showed that an increase in AQP-3 protein concentration, a decrease in BMI, and periodontal status of CPI score 3 also increased the risk of having xerostomia." (PMID 37027451, 2023). "Association of xerostomia status with age, sex, general health status, OHRQOL, unstimulated salivary flow rate, periodontal status, and salivary AQP-3 concentration in patients with periodontal disease." (PMID 37027451, 2023). "Regression analysis showed that body mass index, CPI score 3, and salivary AQP-3 were suitable predictors for presence of xerostomia." (PMID 37027451, 2023). "This study also intended to investigate the potential of using salivary AQP-3 as a screening biomarker for xerostomia." (PMID 37027451, 2023). "Further research is warranted to validate AQP-3 as a screening biomarker for xerostomia in patients with periodontal disease." (PMID 37027451, 2023). "Salivary AQP-3 protein concentration was higher in participants with xerostomia compared to non-xerostomia, providing valuable insight for its potential as a xerostomia biomarker which should be further explored." (PMID 37027451, 2023). "Identification of salivary biomarkers such as AQP-3 as a screening tool may turn out to be a significant move towards developing point-of-care testing for xerostomia in the future." (PMID 37027451, 2023). "In minor salivary glands, AQP-3 staining intensity and localization were reported to be different among these three groups: Patients with Sjögren’s syndrome, patients with subjective xerostomia, and healthy controls." (PMID 37027451, 2023). "However, there are limited published studies investigating aquaporin-3 (AQP-3) protein as a potential screening biomarker of xerostomia in patients with periodontal disease." (PMID 37027451, 2023). "AQP-3 could be a potential screening biomarker for xerostomia in patients with periodontal disease for its early identification may help improve oral health-related quality of life of the individuals." (PMID 37027451, 2023). "Moreover, participants with xerostomia had higher salivary levels of AQP3 than those without xerostomia." (PMID 40725460, 2025). "Moreover, participants with xerostomia had higher salivary levels of AQP-3 than participants who were non-xerostomics." (PMID 37027451, 2023). "Even though the correlations were not strong, it could indicate that xerostomia had an impact on the amount of AQP-3 protein released in saliva which could then be quantitatively assessed." (PMID 37027451, 2023). "Additionally, it has been suggested that AQP-3 and AQP-5 expression as well as the degree of immunoreactivity in the labial salivary glands could be used to differentiate between people who are systemically healthy from those who have objective and subjective xerostomia, or Sjögren’s syndrome." (PMID 37027451, 2023).
enteritis (2 papers, 2016 to 2025). Inflammation of the small intestine. "Furthermore, AQP3 plays an important role in the inflammatory processes in human gastrointestinal infectious diseases.According to our group’s previous study, high temperature and humidity caused intestinal inflammatory factors elevation and minimal enteritis in mice." (PMID 40661958, 2025). "On the other hand, the downregulated expression of several AQPs (AQP1, AQP3, AQP4, AQP7, AQP8, AQP10 and AQP11) in the small and large intestines has been observed in the process of either enteritis or diarrhea." (PMID 27589719, 2016).
esophageal cancer (2 papers, 2020 to 2022). A primary or metastatic malignant neoplasm involving the esophagus. "In esophageal cancer, the expression levels of AQP3 and AQP5 are significantly higher compared with those in adjacent normal tissues." (PMID 35068345, 2022).
esophageal squamous cell carcinoma (2 papers, 2012 to 2020). Esophageal squamous cell carcinoma (ESCC) is a type of esophageal carcinoma (EC) that can affect any part of the esophagus, but is usually located in the upper or middle third. "AQP3 overexpression in esophageal squamous cell carcinoma has been associated with tumor progression and poor prognosis." (PMID 32075009, 2020).
Heat Stroke (2 papers, 2023 to 2024). A condition caused by the failure of body to dissipate heat in an excessively hot environment or during PHYSICAL EXERTION in a hot environment. "Clinical case reports of sauna-associated death and fatal heat stroke have shown increased AQP3-ir in the skin epidermis and Aqp4 expression in the brain." (PMID 39335570, 2024). "Moreover, the AQP3 mRNA expression was downregulated in jejunum tissue samples of rats treated by heat stroke, while AQP3 localization was present from the lamina propria to the crypt following heat stroke." (PMID 38089478, 2023).
Hepatic steatosis (2 papers, 2015 to 2021). Steatosis is a term used to denote lipid accumulation within hepatocytes. "Adipose Aqp3 and hepatic Aqp9 transcripts positively correlated with markers of adiposity and hepatic steatosis." (PMID 26159457, 2015).
Hypertension (2 papers, 2021 to 2023). The presence of chronic increased pressure in the systemic arterial system. "The first candidate gene study identified one SNP rs2231231 from the AQP3 gene associated with PE and later-life hypertension." (PMID 38455895, 2023). "The study concluded that as the AQP3 gene was only associated with hypertension post-pregnancy, the role of the gene might be linked to later-life hypertension risk factors including oxidative stress and metabolic syndrome." (PMID 38455895, 2023). "However, among the four single nucleotide polymorphisms (SNPs), only one intronic SNP rs2231231 from the AQP3 gene, dominant and recessive model of A allele [AA + AC] and [AA] respectively, was associated with PE and the development of hypertension in women 2–16 years post-pregnancy." (PMID 38455895, 2023). "Altogether, these data demonstrate that high TNF-α levels negatively modulate AQP3 in placental tissue, impairing cell migration, and its relationship in a pregnancy affected by hypertension." (PMID 34267676, 2021).
Infertility (2 papers, 2024 to 2026). "AQP3, -7, -8, and -11 are all present in sperm, with the expression levels/activity of AQP3 and AQP7 being shown to be reduced in asthenozoospermic individuals as a possible cause of infertility." (PMID 40927981, 2026).